SHF (Src homology 2 domain containing F)
Description:
Adapter protein which may play a role in the regulation of apoptosis in response to PDGF.
Tractability: PROTAC: its protein half-life has been measured.
Gene: Protein-coding gene on chromosome 15 (45,167,214 to 45,201,175, reverse strand). Ensembl gene ENSG00000138606.
Subcellular location (Human Protein Atlas): Nucleoplasm
Gene Ontology:
Molecular function: phosphotyrosine residue binding
Biological process: signal transduction
Genetic constraint (gnomAD): Loss-of-function variants: 28 observed, 37.31 expected, observed/expected ratio (o/e) 0.75, 90% interval 0.56 to 1.03. The upper end of that interval is the gene's LOEUF score, 1.03, which puts it in group 4 of 6, group 1 being the genes least tolerant of losing a copy. Missense variants: 439 observed, 486.89 expected, observed/expected ratio (o/e) 0.9, 90% interval 0.83 to 0.98. Synonymous variants: 175 observed, 199.46 expected, observed/expected ratio (o/e) 0.88, 90% interval 0.77 to 1.
Homologues: Orthologues: macaque SHF (99% identical), dog SHF (96% identical), rat Shf (93% identical), pig SHF (77% identical), guinea pig SHF (75% identical), chimpanzee SHF (71% identical), tropical clawed frog shf (60% identical), mouse Shf (47% identical). Paralogues in human: SHB (42% identical), SHD (35% identical), SHE (34% identical).
Diseases named in the same sentence as SHF in open-access papers:
SHF is named in the same sentence as 8 diseases in open-access papers, as found by Europe PMC text mining. Sharing a sentence is not in itself a finding about the gene and the disease. The quoted sentences say what the papers report.
breast carcinoma (1 paper, 2015). "In MCF-7 noninvasive breast cancer cells, a reduction in SAFB1 did not appear to significantly alter SHF mRNA expression, whereas in MDA-MB-231 invasive breast cancer cells there was a significant increase in SHF mRNA expression when SAFB1 was reduced." (PMID 26273616, 2015).
glioblastoma (1 paper, 2025). The most malignant astrocytic tumor (WHO grade IV). "SHF is a tumor suppressor of glioblastoma and inhibits glioblastoma progression by negatively regulating STAT3 dimerization." (PMID 40124621, 2025).
glioma (1 paper, 2022). A benign or malignant brain and spinal cord tumor that arises from glial cells (astrocytes, oligodendrocytes, ependymal cells). "The lowest SHF mRNA was observed in grade IV, compared with low grade gliomas (p < 0.01)." (PMID 35843865, 2022). "Additional analysis of the glioma dataset derived from Rembrandt and CGGA datasets showed that SHF mRNA was downregulated both in low and high grade gliomas, compared with non‐tumor brain tissues." (PMID 35843865, 2022).
neuroblastoma (1 paper, 2015). Neuroblastoma (NB) is the most common solid, extracranial childhood tumor. "Although the function of SHF is not fully understood, evidence has shown that overexpression of SHF significantly decreases the rate of growth factor-induced apoptosis in neuroblastoma cells." (PMID 26273616, 2015).
SHF also shares sentences with these, for which no sentence is quoted: Alzheimer disease (2 papers); tumor (2); depression (1); invasive breast carcinoma (1).